IL1B (interleukin 1 beta)
Diseases named in the same sentence as IL1B in open-access papers (continued):
Sharing a sentence is not in itself a finding about the gene and the disease.
periodontal disease (continued). "Although some results did not support that the IL-1β SNP could be identified as a risk factor for CP, but the synergistic interactions of the some genotypes of IL-1β SNPs with environmental factors might play an important role in the pathogenesis of periodontal disease." (PMID 30755190, 2019). "Due to the lack of sufficient data, we could not detect whether IL-1β rs1143627 polymorphism is a co-factor of smoking in periodontal disease." (PMID 28404906, 2017). "When added to primary cultured oral fibroblasts, IL1β upregulates IL6, IL1β, IL8, and TNFα,5,17 induces AT1R expression in different cell types, and is an important cytokine in periodontal disease." (PMID 40929402, 2025). "Interleukin-1 beta (IL-1β) and matrix metalloproteinase-8 (MMP-8) are prominent salivary biomarkers that provide valuable insights into the detection and progression of periodontal disease." (PMID 40283051, 2025). "The choice to investigate IL-1β and MMP-8 in this study was based on their complementary roles in the pathogenesis of periodontal disease." (PMID 40283051, 2025). "IL-1β and MMP-8 help fill this gap by providing complementary insights into the progression of periodontal disease." (PMID 40283051, 2025). "Periodontal disease involves the chronic production of inflammatory cytokines, such as TNF-α, IL-1β, IL-6, IL-8, and IL-17, which contribute to the destruction of soft and hard tissues." (PMID 40867800, 2025). "Analogous to periodontal disease, the pathogenesis of IBD involves aberrant immune system activation, with pro-inflammatory mediators, including TNF-α, IL-1β, and IL-6, orchestrating the immune microenvironment and driving disease progression." (PMID 40002889, 2025). "Several pro-inflammatory interleukins, notably IL-1β, IL-6, TNF-α, and IL-17, have been proposed as biomarkers for periodontal disease." (PMID 41155385, 2025). "This study aimed to comparatively evaluate the levels of Metrnl, pro-inflammatory (IL-1β), and anti-inflammatory (IL-10) cytokines in salivary and GCF samples in the presence of periodontal disease." (PMID 39964474, 2025). "The complementary roles of IL-1β and MMP-8 suggest that their combined analysis can enhance the accuracy of periodontal disease diagnostics and staging." (PMID 40283051, 2025). "The combined application of IL-1β and MMP-8 represents a significant step forward in diagnosing and managing periodontal disease." (PMID 40283051, 2025). "In particular, IL-1β and TNF-α are the most extensively studied and are strongly correlated with the development of periodontal disease." (PMID 41154468, 2025). "The correlations between salivary biomarkers and clinical parameters reveal the distinct but complementary roles of IL-1β and MMP-8 in periodontal disease progression." (PMID 40283051, 2025). "This study highlights the potential role of salivary biomarkers, including IL-1β and MMP-8, in assessing the severity of periodontal disease." (PMID 40283051, 2025). "This study investigates and compares the utility of two salivary biomarkers, interleukin-1 beta (IL-1β) and matrix metalloproteinase-8 (MMP-8), in the early detection and staging of periodontal disease." (PMID 40283051, 2025). "The authors investigated the role of MMP-8, 9, IL-1β, IL-6, and TNF-α along with MIP-1α and found that MIP-1α had the highest discriminatory role in periodontal disease among adults." (PMID 38433948, 2024). "The RT-qPCR results indicated a significant increase in the expression of key proinflammatory cytokines, such as IL-1β, TNF-α, and IL-6, in brain tissues as a result of Pg-induced periodontal disease." (PMID 38892314, 2024). "Cytokines such as IL-1β, TNF-α, IL-6, and RANKL are pivotal in managing the immune response in periodontal diseases." (PMID 38595889, 2024). "(i) If IL-1β, IL-6, AND TNF-α are elevated in the serum of patients with periodontal disease OR COVID-19 infection." (PMID 37106750, 2023).
periodontal disease (continued). "Four of them, IL1B (p = 0.023), IL1RN (p = 0.048), BGLAP (p = 0.0372) and PTK2 (p = 0.0075) were down-regulated in the periodontal disease and implant rejection group, and only one was overexpressed: FOXO1A (p = 0.0552)." (PMID 37175429, 2023). "The imbalance in cytokine production namely interleukin (IL)-6, IL-1β, and interferon (INF)-γ with immunosuppression due to periodontal diseases also play a role in the etiopathogenesis of MDD." (PMID 36915833, 2023). "The purpose of this study was to investigate the effect of MF on the MMPs, IL-1β and IL-8 production from HGFs to gain insights into the mechanisms by which MF may alter the gingival tissue response and explore its potential anti-inflammatory role in periodontal diseases." (PMID 37189090, 2023). "Known biomarkers for periodontal disease include CRP, IL-1β, TGF-β, VEGF, proteolytic degradation products (CTx), and matrix metalloproteinases (MMPs)." (PMID 37262024, 2023). "These salivary cytokines, particularly IL-1β, IL-6, and TNF-α, offer reliability in assessing the severity of periodontal disease, making them valuable markers for monitoring disease progression." (PMID 38192959, 2023). "Correlation with clinical parameters: Biomarkers such as IL-1β, MMP-8, and S100A8 are extensively researched in periodontal disease." (PMID 38192959, 2023). "Many inflammatory mediators, including the inflammatory cytokines interleukin-1 beta (IL-1β), tumor necrosis factor-alpha (TNF- α), and prostaglandin E2 (PGE2) have been found in saliva during the development and progression of periodontal disease." (PMID 36747174, 2023). "A recent systematic review evaluated macrophage inflammatory protein-1α (MIP-1α), IL-1β, IL-6 and MMP-8 as diagnostically acceptable biomarkers for periodontal disease, and the combination of IL-6 and MMP-8 showed the best diagnostic performance." (PMID 35562715, 2022). "The findings of the present study show that IL-39, IL-1β, and periostin levels were elevated in GCF in presence of periodontal disease." (PMID 35986791, 2022). "The aim of this study is to evaluate the gingival crevicular fluid (GCF) IL-39 levels in periodontal diseases and health and to correlate them to GCF levels of IL-1β and periostin." (PMID 35986791, 2022). "Pro-inflammatory cytokines, IL-1β, IL-6, TNF-α, and IFN-γ, have a major role in the pathogenesis of periodontal disease and were also detected in healthy GCF samples." (PMID 35048035, 2021). "Inflammatory cytokine biomarkers, such as interleukin-1 beta (IL-1β), interleukin-6 (IL-6), and tumor necrosis factor alpha (TNF-α) are significantly elevated in patients with cardiovascular and periodontal disease." (PMID 34299815, 2021). "In an experimental periodontal disease model, gliclazide treatment reduced myeloperoxidase activity, MDA, IL-1β and TNF-α levels via downregulation of PI3K and AKT (Araújo and Morais, 2019)." (PMID 34227646, 2021). "A recent systematic review reported that the combination of MIP-1α, IL-1β, IL-6, and MMP-8 was acceptable as biomarkers for diagnosing periodontal disease." (PMID 34199256, 2021). "IL-1α, IL-1β, and TNF-α as predictive biomarkers for the diagnosis of periodontal disease were analyzed by ROC curves." (PMID 34199256, 2021). "For example, several cytokines and chemokines known to be involved in the etiology of periodontal disease were also detected in clinically healthy GCF, such as TNF-α and IL-1β." (PMID 35048035, 2021). "Salivary IL-1β, MMP-8, ICTP, and Pg showed significant effectiveness for diagnosing periodontal disease." (PMID 34001101, 2021). "A recent study showed that levels of IL-1β, TNF-α, and other inflammatory cytokines can be used to accurately monitor the progress, treatment effectiveness, and prognosis in periodontal disease." (PMID 34299815, 2021). "Our results indicated that P. gulae infection induced overexpression of IL-1β, IL-8, and COX-2, potentially leading to inflammation involved in deterioration of periodontal disease." (PMID 32080231, 2020).
periodontal disease (continued). "Increased serum and salivary IL-1β levels induced the increase in serum and salivary NGAL levels from healthy to severe periodontal disease." (PMID 32997091, 2020). "Another study demonstrated that the increased IL-6, IL-1β and MCP-1 mRNA levels were observed in a mouse model of experimental periodontal disease, and this was suppressed by an Am80 treatment." (PMID 32651445, 2020). "On the other hand, biomarkers of periodontal disease progression in GCF alone (MMP-8, MMP-9, Osteoprotegerin, C-reactive Protein and IL-1β) provided low sensitivity and high specificity values of 23% and 95%, respectively." (PMID 31817894, 2019). "The levels of inflammatory mediators (IL-1β, IL-6, β-glucuronidase, and TNF-α) in saliva and in serum (except IL-6) significantly increased with severity of periodontal disease." (PMID 29017560, 2017). "Therefore, the questions of whether IL-1β rs1143627 polymorphism is related to periodontal disease or not, and whether there is a difference of such relationship between CP and AgP still remain uncertain." (PMID 28404906, 2017). "Salivary levels of IL-1β, CRP and NO levels have been reported to be higher in patients with periodontal disease when compared to healthy dentate patients." (PMID 28253297, 2017). "Telmisartan and Olmesartan significantly reduced pro-inflammatory cytokines such as IL-1β and TNF-α, which resulted in significant preservation of bone in periodontal disease." (PMID 24819928, 2014). "During the pathogenesis of periodontal disease, the host immunoinflammatory response to plaque bacteria produces destructive cytokines such as TNF-α, IL-1β, and MMPs." (PMID 24453415, 2013). "In this study, using a model of periodontal disease, animals treated with 10 mg/kg of Atorvastatin also had reduced levels of TNF-α and IL-1β." (PMID 24130702, 2013). "Anticytokine therapy for periodontal diseases mainly targets TNF-α, IL-1β, and IL-6, because they are essential for the initiation of inflammatory immune reactions and are produced for prolonged periods in inflammatory disease." (PMID 20407652, 2009). "According to the findings of this study, IL-1β and MMP-8, as salivary biomarkers, may be helpful in diagnosing periodontal disease." (PMID 40283051, 2025). "Light CS and ES users without periodontal disease show no change in clinical periodontal markers, whole-salivary CL, or Il-1β levels following NSPT." (PMID 40291822, 2025). "For instance, gingival crevicular fluid (GCF) levels of PGE2 and IL-1β are higher in type 1 diabetic patients with gingivitis or periodontitis compared to non-diabetic individuals with the same periodontal disease severity." (PMID 39852378, 2025). "By assessing IL-1β and MMP-8 levels in conjunction with clinical parameters, this study highlights the dynamic interplay between inflammatory and destructive processes in periodontal disease." (PMID 40283051, 2025). "In addition, elevated levels of salivary IL-1β, IL-6, and TNF-α reflect activation of the local inflammatory response, which is consistent with previous studies on salivary biomarkers in periodontal disease." (PMID 41301927, 2025). "Salivary cytokines, particularly IL-1β, IL-6, and TNF-α, can serve as reliable markers for periodontal disease severity and may aid in monitoring disease progression." (PMID 38192959, 2023). "This is consistent with a previous clinical study which revealed that diabetics had significantly higher levels of IL-1β in GCF compared with non-diabetic controls who were matched in periodontal disease severity." (PMID 37047282, 2023). "In light CS and ENDS users without periodontal disease, clinical periodontal parameters and whole-salivary CL and Il-1β levels remain unchanged after NSPT." (PMID 36141565, 2022). "TNFα (p = 0.0038), MCP1 (CCL2) (p = 0.0493), IL-1β (P = 0.0043), and IL-8 (p = 0.0035) were increased in OSCC compared to control only while MIP1β (CCL4) (p < 0.0365) was increased in OSCC patients compared to periodontal disease patients." (PMID 35048057, 2021).
periodontal disease (continued). "However, in the 11 studies included in this study, IL-1β, MMP-8 and TNF-α in saliva were the most frequently observed biomarkers in periodontal disease patients compared to healthy controls." (PMID 33383828, 2020). "The disturbance of the lipidic metabolism could be explained by the inhibition of the lipase lipoprotein secondary to the release of pro-inflammatory cytokines, such as IL-1β and TNF-α during periodontal diseases." (PMID 31640685, 2019). "There is no agnostic GWAS evidence for the genetic control of IL-1β expression in periodontal disease." (PMID 30206230, 2018). "Although the present study reports that the DPIE enhanced cytokine production in IL-1β-induced GFs, further investigations are still necessary to clarify whether DPIE has beneficial or harmful effects on the progression of periodontal diseases in vivo." (PMID 29932110, 2018). "The elevated concentrations of serum IL-1β, β-glucuronidase, and TNF-α-accompanying saliva mediators suggested periodontal disease might be one of the factors triggering a systemic inflammatory response." (PMID 29017560, 2017). "Inflammatory mediators includinginterleukin-1 beta (IL-1β), IL-6, tumor necrosis factor alpha (TNF-α) and beta-glucuronidase (β–glucuronidase) were tested and analyzed among women with overall periodontal disease (n = 442) or moderate/severe periodontal disease (n = 247)." (PMID 27978823, 2016). "The elevated concentrations of serum IL-1β, β-glucuronidase, TNF-α accompanying with the saliva mediators suggested periodontal disease might be one of the factors triggering a systemic inflammatory response." (PMID 27978823, 2016). "Although differences in TNF-α and TNF-β were not correlated with the periodontal disease treatment outcome, differences in IL-1α, IL-1β, IL-6, and IL-8 were significantly higher in the ET group in this study." (PMID 25884025, 2015). "Periodontal disease characteristically exhibits high levels of salivary IL-8, MMP-9 and IL-1β." (PMID 24915044, 2014). "Thus, IL-1β and MMP-8 reflect distinct but complementary processes—early inflammation and structural destruction—highlighting their dual relevance for diagnosing and monitoring periodontal disease." (PMID 40283051, 2025). "In addition to the biomarkers assessed, the inclusion of other parameters such as MMP-8, IL-1β, and TNF-α could provide comprehensive insights into the pathogenesis of periodontal disease." (PMID 41300847, 2025). "Also, they showed that IL-1β and TNF-α are promising biomarkers in detecting periodontal disease." (PMID 37224312, 2023). "Nucleotide-binding oligomerization domain (NOD)-like receptor (NLR) family pyrin domain containing 3 (NLRP3) inflammasome-mediated interleukin-1β (IL-1β) is significantly involved in periodontal diseases, and notably P. gingivalis enables to modulate the induction and expression of NLRP3." (PMID 32903638, 2020). "Moreover, IL-1β has been detected in the gingival fluid and tissues of patients with periodontal disease, but not in healthy individuals." (PMID 30142971, 2018). "Moreover, according to recent systematic reviews and meta-analyses, salivary IL-1β, IL-6, and MMP-8 are among the five promising biomarkers that have been identified as eligible candidates for the diagnosis of periodontal diseases; while IL-10 may have a strong regulatory effect on immune responses." (PMID 35368315, 2022). "Serum IL-1β and TNF-α levels were significantly higher in women with overall periodontal disease compared with women without periodontal disease." (PMID 27978823, 2016). "Serum IL-1β, β–glucuronidase and TNF-αwere significantly higher in women with moderate/severe periodontal disease, compared with women without periodontal disease." (PMID 27978823, 2016). "Therefore, elevated IL-1β GCF levels, but not plasma levels, were suggested as reliable inflammatory biomarkers in periodontal diseases." (PMID 30755772, 2019).
periodontal disease (continued). "The authors concluded, it is likely that elevated IL-6 reflects the degree of subclinical inflammation in periodontal tissues, which can be a link between periodontal disease and OSAS, and the presence or severity of OSAS does not affect the level of IL-1β and IL-21 in either plasma or saliva." (PMID 26998377, 2016). "Although the changes in salivary IL-1β and MMP-8 levels after non-surgical periodontal therapy were not significant, salivary cytokines could be used to confirm the effect of periodontal therapy or diagnose periodontal disease." (PMID 33383828, 2020). "Significantly increased concentrations of inflammatory mediators of IL-1β, IL-6, TNF-α and β-glucuronidase in saliva and IL-1β, β-glucuronidase and TNF-α in serum were found among pre-conception women with moderate/severe periodontal disease, compared with women without periodontal disease." (PMID 27978823, 2016).